RBP4 (retinol binding protein 4)
Diseases named in the same sentence as RBP4 in open-access papers (continued):
Sharing a sentence is not in itself a finding about the gene and the disease.
cancer (continued). "Through its direct influence on cancer cells, increased endothelial dysfunction, and impairment of blood arteries within the tumor, RBP4 increases the metastatic potential of breast cancer tumors." (PMID 39434876, 2024). "The expression level of retinol‐binding protein 4 (RBP4) protein is closely related to liver damage and plays an important role in the diagnosis and prognosis of cancer." (PMID 34889069, 2022). "With the deepening of studies, researchers found that the expression level of RBP4 was closely related to cancers." (PMID 34889069, 2022). "Retinol-binding protein (RBP4)-related disruption of retinol metabolism was reported to participant in malignant tumors." (PMID 36685838, 2022). "First, RBP4 was closely correlated with metabolism and has been recognized as a link between adiposity and cancer, however, here we didn't find any significant correlation between the body mass index with the RBP4 levels." (PMID 36632438, 2022). "In the present study, these RBP4-related genes were also involved in regulating the metabolic microenvironment, indicating that the regulation of cancer cell metabolism can be either direct or indirect via RBP4 expression." (PMID 33834191, 2021). "In vitro studies showed increased invasive and clonogenic potential of cancer cells treated with or overexpressing RBP4." (PMID 32156052, 2020). "The results showed that the top genes positively associated with PC1 included RBP4, SLC27A5, and PCK2, all of which were known tumor-related genes and correlated with cancer patients’ survival." (PMID 32231683, 2020). "Apart from the influence of RBP4 in vitro on endothelial cells, RBP4 has also been reported to influence cancer cells." (PMID 32156052, 2020). "In vitro 24 h preincubation of cancer cells with RBP4 significantly increased lung settlement of 4T1 cells." (PMID 32156052, 2020). "The incubation of cancer cells for 24 h before intravenous injection should at least represent the effect of RBP4 on cancer cells." (PMID 32156052, 2020). "All these experimental schedules resulted in the increase of lung settlement by cancer cells, indicating that the effect of RBP4 on both cancer and endothelial cells is important." (PMID 32156052, 2020). "Studies have shown various correlations between RBP4 plasma/tumor tissue levels and the development of certain types of cancer." (PMID 32156052, 2020). "The RBP4 level in cancer tissues, shown in brown, was significantly increased comparing to the benign ovarian tissues, which only exhibited weak staining." (PMID 29642915, 2018). "Then the transwell migration assays showed that RBP4 overexpression can greatly enhance cancer cell migration in both cell lines." (PMID 29642915, 2018). "To test if RBP4 induced cancer cell migration is RhoA/Rock1 dependent, we added Y-27632 to our RBP4 overexpression cells." (PMID 29642915, 2018). "To explore how RBP4 exerts its effect on cancer cells, we tested the expression level of several key players in tumorigenesis related signaling." (PMID 29642915, 2018). "Further studies were in demand to fully elucidating the RBP4 signaling pathways that related to cancers." (PMID 29642915, 2018). "Further analysis indicates that optical density of RBP4 positive expression is 0.58 ± 0.47 for cancer tissues and 0.35 ± 0.06 for normal ovarian tissues." (PMID 25250314, 2014). "Preliminary investigation showed that men and women with a BMI of 40.0 and above had a death rate from all cancers combined of 52%, which was 88% higher than their normal-weight counterparts, indicating that RBP4 also plays a role in cancer." (PMID 25250314, 2014). "Compared with the other three groups, RBP4 levels as detected by ELISA were significantly higher (3–8 times higher) in cancer patient sera (P < 0.05)." (PMID 25250314, 2014). "The positive expression of RBP4 in cancer tissues shown in brown is significantly increased as compared to the normal ovarian tissue, which shows weak IHC staining." (PMID 25250314, 2014).
cancer (continued). "In contrast, molecular mechanisms for regulation of cancer cell growth by RBP4 must be clarified in future studies." (PMID 23708710, 2013). "RBP4 has been shown to alter lipid profile in several clinical trials with fenretinide, a synthetic retinoid designed for cancer therapy that increases renal clearance of RBP4." (PMID 24223837, 2013). "RBP4 also has been demonstrated to be involved, to some extent, in the development of inflammation and cancer." (PMID 22363757, 2012). "In our study, we identified RBP4 as a prospective candidate but further investigation of its function in the pathogenesis of cancer development is required." (PMID 22363757, 2012). "In view of the known roles of retinol in controlling cellular differentiation and the abnormal expression of RBP4 in cancer, these data contribute to understanding LA-12 action as an anti-cancer agent and identify RBP4 as a serum marker for LA-12 activity." (PMID 22040120, 2011). "High expression levels of RBP4 were associated with poor overall survival (OS), disease-specific survival (DSS), and progression-free interval (PFI) in specific cancers, notably in BRCA, HNSC, and STAD, whereas it was a favorable prognostic factor in cancers such as KIRP and MESO." (PMID 40004479, 2025). "In addition, we conducted co-expression analysis using the TCGA database to reveal the association of RBP4 and RBP7 with immune checkpoints in pan-cancer." (PMID 41301068, 2025). "DNA methylation analysis suggested that the methylation of RBP4 may play a role in its regulatory mechanisms across cancer types." (PMID 40004479, 2025). "In conclusion, increasing evidence suggests that RBP4 might be an emerging biomarker in cancers, and its expression can affect patient prognosis." (PMID 40004479, 2025). "Those fundings suggested RBP4 could be a potential novel biomarker for the diagnosis, treatment, and progression of various cancers, including breast cancer, hepatocellular carcinoma, and colorectal cancer." (PMID 40004479, 2025). "Notably, RBP4 expression showed a strong positive correlation with hematopoietic stem cell infiltration in most cancers." (PMID 40004479, 2025). "This discrepancy may be caused by the fact that the analyzed samples in our study were sourced from large-scale public databases, rather than a limited number of tumor specimens, and the expression of RBP4 in many cancers was reported for the first time." (PMID 40004479, 2025). "First, correlation analysis determined significant correlation of 18 proteins with cancer-associated inflammation, including 9 proteins correlated positively such as C8A, A2GL, and ceruloplasmin (CERU), while another 9 proteins including retinol-binding protein 4 (RET4) were correlated negatively." (PMID 38911905, 2024). "Overexpression of RBP4 promoted cancer cell migration and proliferation." (PMID 38913193, 2024). "Molecularly, RBP4 induced the expression of cancer progression factors MMP2 and MMP9." (PMID 38913193, 2024). "It has been suggested that RBP4 is an adipokine that connects fat and cancer." (PMID 39434876, 2024). "The RBP4+NTS+ cancer cell subset is unique to left-sided CRC." (PMID 34793335, 2022). "Notably, we identified a potentially novel RBP4+NTS+ subpopulation of cancer cells that exclusively expands in left-sided CRC." (PMID 34793335, 2022). "RBP4 may also act as a molecular bridge between the dysregulation of metabolic processes and cancers." (PMID 33834191, 2021). "We also show that vitamin A decreased urothelial atypia and therefore can speculate that vitamin A exerts its protective effects by neutralizing Stra6 and Rbp4 expression, leading to diminished cancer stem cell preservation." (PMID 32605249, 2020). "Furthermore, the direct effect of RBP4 on cancer cells through increased migratory and colony-forming properties contributes to the final prometastatic effect." (PMID 32156052, 2020).
cancer (continued). "Moreover, the highest number of cancer cells in the lungs were observed in the experiment where both effects occurred: injection of cancer cells 1 h after RBP4 injection." (PMID 32156052, 2020). "On the other hand, when cancer cells were injected 3 h after RBP4 injection, only the effect of RBP4 on the endothelial cells could be observed." (PMID 32156052, 2020). "MMP-2 and MMP-9, which are key factors in cancer metastasis, were affected by RBP4 overexpression." (PMID 31212896, 2019). "This suggested that RBP4 stimulates cancer cell migration along with cell proliferation." (PMID 31212896, 2019). "The observation further confirmed the effect of RBP4 expression on cancer cell migration." (PMID 29642915, 2018). "Moreover, we show that knockdown of RBP4 significantly reduce cancer cell migration and proliferation as well as expressions of oncogenic factors." (PMID 29642915, 2018). "The MMP-2 and MMP-9, key factors in cancer metastasis, were induced by RBP4 overexpression." (PMID 29642915, 2018). "In contrast, cancer cells were less mobile when RBP4 was knocked down with siRNA." (PMID 29642915, 2018). "Until now, study results of serum RBP4 concentration in cancers are uncertain." (PMID 29190912, 2017). "RBP4 might provide a new direction for cancer biomarker research, which needs to be confirmed by much more studies." (PMID 29190912, 2017). "RBP4 is a plasma protein involved in the transport of retinol, which serves as a differentiation-inducing molecule in various stem cells and is aberrantly expressed in cancer." (PMID 22040120, 2011). "Our findings suggest that RBP4 could serve as a novel biomarker and therapeutic target in cancer, although further experimental studies are required to elucidate its precise mechanisms in specific cancer types." (PMID 40004479, 2025). "However, a comprehensive pan-cancer analysis of RBP4’s expression, prognostic significance, and functional associations across various cancers is lacking." (PMID 40004479, 2025). "Therefore, the decrease in RBP4 expression level in cancer tissues might be a new indicator for early detection of cancers in the clinic." (PMID 34889069, 2022). "Therefore, we assumed that injecting RBP4 1 h prior to the injection of cancer cells may allow to observe the combined effects of RBP4 on cancer cells and endothelial cells." (PMID 32156052, 2020). "Moreover, the overexpression of RBP4 in cancer cells further increased the metastatic potential of the 4T1/RBP4 cell line, and for the nonmetastatic 67NR cell line, we could detect cancer cells in the lungs of 67NR/RBP4 tumor-bearing mice." (PMID 32156052, 2020). "Moreover, the plasma levels of RBP4 were higher in aged mice bearing cancer than in young mice." (PMID 32156052, 2020). "Moreover, knockdown of RBP4 greatly reduced cancer migration." (PMID 29642915, 2018). "Available information suggests the possibility that RBP4 may be a link between obesity and cancer." (PMID 29190912, 2017). "RBP4 was also negatively correlated with CD4+ Th2 T cell infiltration across 33 cancers, with statistically significant correlations being observed in 13 cancer types." (PMID 40004479, 2025). "Reduction in RBP4 levels results in inactivation of N-cadherin, MMP2, -3, -9, and an increase in E-cadherin, which also proves the roles of RBP4 in cancer cell migration." (PMID 41007818, 2025). "Further analysis of single-cell transcriptome data revealed the expression profiles of RBP4 and RBP7 in cancers." (PMID 41301068, 2025). "Therefore, RBP4 may play multiple roles in different types of cancer." (PMID 36632438, 2022). "RBP4 expression was low in HCC and was also down-regulated in pan-cancers compared with normal tissues." (PMID 33834191, 2021). "The proposed mechanisms of RBP4 effects on cancer cells are dependent on the activation of the signaling receptor and transporter of retinol STRA6 by bound RBP4 and further transduction of the JAK2-STAT3 signaling cascade." (PMID 32156052, 2020).
cancer (continued). "The overexpression of RBP4 stimulated the expression of matrix metalloproteinase MMP-2 and MMP-9, which degraded extracellular matrix and enabled cancer cells migration." (PMID 29642915, 2018). "At molecular level, cancer progression factors MMP2 and MMP9 are induced in response to RBP4 overexpression." (PMID 29642915, 2018). "Multiple tumor suppressors were expressed at lower levels in EBVaGCs including five (TFF2, RBP4, HOXA9, LRRN1, and RAP1GAP) that are known to be hypermethylated in cancers." (PMID 23671415, 2013). "RBP4 exhibited positive or negative correlations with various immune cell types across the majority of cancer types analyzed." (PMID 40004479, 2025). "RBP4 activates STRA6, leading to activation of Janus kinase and STAT3/STAT5, which results in pro-inflammatory response and tumorogenesis.This results in cancer progression, migrations, and metastasis." (PMID 41007818, 2025). "RBP4 and SERPINA3 were expressed in both the cancer cell cytoplasm and the immune cell cytoplasm." (PMID 37313408, 2023). "Other proteins, such as CLEC3B, ITIH4, SAA1, and C20ORF3 exhibited increased expression in cancer EVs, while RBP4, SAA1, and DBP did not exhibit significant differences between normal and cancer samples." (PMID 33808296, 2021). "We can therefore assume that this effect is not dependent on the direct effect of RBP4 on cancer cells." (PMID 32156052, 2020). "The effect of RBP4 on tumor tissue and cancer cells in this model is not dependent on STAT3 phosphorylation." (PMID 32156052, 2020). "In summary, the plasma level of RBP4 in young and old mice bearing metastatic 4T1 cancer is higher compared to mice with non-metastatic 67NR." (PMID 32156052, 2020). "We carried out western blot analysis (data not shown) and identified that Retinol-binding protein 4 (RBP4) was upregulated in sera from cancer patients." (PMID 25250314, 2014). "As results of initial validation by western blotting in relatively advanced cases and further validation including the less advanced cases by western blotting, the expression levels of the four proteins ApoA-IV, GC, RBP4, and CLEC3B were greater in cancer patients than in controls." (PMID 22091389, 2011). "However, the consequence of RBP4 overexpression on cancers and the mechanism of action of RBP4 in cancers are not clear." (PMID 29642915, 2018). "A direct relationship between RBP4 and cancer, however, has not been elucidated." (PMID 23708710, 2013). "Our analysis revealed a negative correlation between RBP4 expression and CD4+ Th2 cell infiltration in several cancers from the TCGA database." (PMID 40004479, 2025). "The expression of RBP4, SAA1, and DBP in cancer EVs was not significantly altered, compared to that in normal EVs." (PMID 33808296, 2021).
tumor (38 papers, 2013 to 2025). "The results of several microarray- or transcriptomic-based studies have shown that RBP4 is associated with the level of immune infiltration in tumor tissue." (PMID 37313408, 2023). "In contrast to the serum level, RBP4 expression was low in HCC tissues compared with normal tissues, and low RBP4 expression levels were associated with advanced tumor stages and poorer overall survival." (PMID 36632438, 2022). "RBP4 expression was also significantly different based on age (41–60 years old versus 61–80 years old), and low RBP4 expression levels were associated with advanced tumor stages and grades." (PMID 33834191, 2021). "Previous studies have confirmed that RBP4 is primarily associated with biological processes related to lipid metabolism, supporting that RBP4 may influence tumor biology through metabolic reprogramming." (PMID 40004479, 2025). "Therefore, understanding the relationship between RBP4 expression and tumor-associated immune cell infiltration is crucial." (PMID 40004479, 2025). "RBP4+ tumor cells were associated with hypoxia processes and extensive cell-to-cell communication." (PMID 38913193, 2024). "The RBP family, especially RBP4, has been implicated to be associated with tumour invasion and metastases, which could involve the hypermethylation in the gene body." (PMID 37071990, 2023). "To further explore the relationship between RBP4 expression and clinical information, we applied the HCC tumor tissues transcriptional profiles, and examined possible subgroup associations with RBP4 expression based on patient age, gender, race, tumor grade, TNM staging, and lymph node metastasis." (PMID 33834191, 2021). "We observed that the RBP4 promoter methylation level was significantly and negatively related to most tumor tissues but was positively related to TGCT." (PMID 40004479, 2025). "Together, these independent results strengthen the interpretation that elevated, tumor-intrinsic RBP4 expression contributes to CRC progression." (PMID 41007818, 2025). "Although our study provides insights into the potential impact of RBP4 on tumor cell migration and proliferation, further experimental validation is essential to elucidate the underlying molecular mechanisms." (PMID 40004479, 2025). "In gastric cancer cells, RBP4 expression is upregulated, and its silencing inhibits tumor proliferation, migration, and invasion." (PMID 41007818, 2025). "Normal liver and kidney tissues had strong RBP4 IHC staining, while tumor tissues had moderate staining." (PMID 40004479, 2025). "RBP4 expression levels were examined in 33 tumor types, and correlations with clinical outcomes, immune cell infiltration, DNA methylation, and gene mutations were assessed." (PMID 40004479, 2025). "Recent studies have highlighted that RBP4 is not only a metabolic regulator but also a contributor to tumor biology." (PMID 41007818, 2025). "Such a mechanism highlights the relevance of RBP4 as a possible modulator of cell division dynamics within the tumor context." (PMID 41007818, 2025). "RBP4+ tumor cells displayed the highest communication pattern along different types of LIHC malignant cells, showing intensive interactions with the endothelial cells, myeloid cells and CAFs." (PMID 38913193, 2024). "In our study, RBP4+ tumor cells were highly enriched with hypoxia process and intensive cell-to-cell communication." (PMID 38913193, 2024). "The finding that NF-κB controls the expression of vascular endothelial growth factor (VEGF) thus contributing to tumor angiogenesis can give support to the possible involvement of NF-κB signaling in the mechanism of the effects of RBP4." (PMID 39434876, 2024). "RBP4+ tumor cells were highly enriched with hypoxia process and intensive cell-to-cell communication." (PMID 38913193, 2024). "Overexpression of RBP4 resulted in enhanced GBM proliferation capacity, which was consistent with clinical findings on the positive correlation between RBP4 level and tumor size." (PMID 36632438, 2022).